GAK (cyclin G associated kinase)
Diseases named in the same sentence as GAK in open-access papers (continued):
Sharing a sentence is not in itself a finding about the gene and the disease.
diabetic kidney disease (1 paper, 2020). Progressive kidney disorder caused by vascular damage to the glomerular capillaries, in patients with diabetes mellitus. "Reduced glomerular GAK expression is observed in patients with impaired kidney function due to CKD and diabetic kidney disease." (PMID 33208557, 2020). "Furthermore, we also observed a striking 6.947-fold reduction in GAK expression that correlated with a reduction in glomerular filtration rate (GFR) in this CKD cohort, which was further validated in other CKD and diabetic kidney disease (DKD) cohorts in different data sets." (PMID 33208557, 2020).
Obesity (1 paper, 2022). Accumulation of substantial excess body fat. "ASH1L and GAK were previously reported to be associated with obesity traits such as BMI and waist-hip ratio in GWAS of UK Biobank39." (PMID 36329257, 2022).
rheumatoid arthritis (1 paper, 2023). A chronic, systemic autoimmune disorder characterized by inflammation in the synovial membranes and articular surfaces. "Baricitinib, a Janus kinase 1/2 inhibitor approved by the FDA for the treatment of rheumatoid arthritis, was recently found to inhibit both AAK1 and GAK and used as a potential inhibitor for 2019-novel CoV acute respiratory disease." (PMID 37196766, 2023).
schwannoma (1 paper, 2021). A benign, usually encapsulated slow growing tumor composed of Schwann cells. "In a compatible experiment using lysate prepared from schwannomas from a genetically engineered murine model (GEMM), Nf2flox/flox;Postn-Cre mice, a MIB competition assay identified FAK1 (PTK2) and GAK as the primary targets of brigatinib." (PMID 34264955, 2021). "Collectively, these data identify brigatinib as a direct and potent inhibitor of multiple kinases, including FAK1 (PTK2) and FAK2 (PTK2B), and novel targets, GAK and TNK2, in both arachnoid and schwannoma cells." (PMID 34264955, 2021). "Similarly, the non-RTK PTK2/FAK and the serine-threonine kinases GAK, RPS6KA3/RSK2, and MARK3 were also found to be greatly suppressed in brigatinib-treated schwannoma cells." (PMID 34264955, 2021).
stomach adenocarcinoma (1 paper, 2019). "The stomach adenocarcinoma dataset revealed that overall survival was significantly altered as a result of differential expression of four HSPs - CCT8, DNAJC19, GAK and SEC63." (PMID 30578123, 2019).
cancer (18 papers, 2005 to 2026). A tumor composed of atypical neoplastic, often pleomorphic cells that invade other tissues. "From the short list of 12 mRNAs that met these criteria, we focused our further analysis on GAK mRNA, as reduced GAK levels had been linked to appearance of abnormal mitoses and elevated GAK levels were reported in several different cancers." (PMID 28472763, 2017). "The identification of the druggable target GAK capable of selective toxicity in FBXW7-deficient cancers has broad therapeutic applications across numerous tumour types." (PMID 28829765, 2017). "Nuclear colocalization of GAK with its association partner AR was observed in cancer cells from all of the GAK-positive surgical specimens." (PMID 24971999, 2014). "GAK is localized principally in the nucleus in cancer cells and nuclear GAK overexpression was reported in surgical specimens from PC patients." (PMID 35335890, 2022). "The treatment was associated with a significant decrease of the expression of cyclin G-associated kinase (GAK), which has an important role in clathrin-mediated membrane trafficking and is often overexpressed in cancer cells." (PMID 32268584, 2020). "The availability of the GAK crystal structure provides the basis for the development of more specific inhibitors for the treatment of these cancers." (PMID 24438162, 2014). "Cyclin G-associated kinase (GAK), a key player in clathrin-mediated membrane trafficking, is overexpressed in various cancer cells." (PMID 24971999, 2014). "Nuclear localization of GAK and the AR was detected in the nuclei of cancer cells from all GAK-positive surgical specimens (n = 4 patients with a Gleason score ≤7 and n = 5 patients with a Gleason score ≥8)." (PMID 24971999, 2014). "Taken together, the results presented here suggest that GAK, which is overexpressed in many cancer cells, is a novel candidate for promising targeted chemotherapy." (PMID 24971999, 2014). "Taken together, these results indicate that GAK is modified and overexpressed in cancer cells, especially metastatic cells." (PMID 24971999, 2014). "Similar to the result in the MCF-7 cells, ZAK (ranked 3rd), MEK5 (ranked 7th) and GAK (ranked 9 th) were again found in the cancer-specific target set for BxPC-3 cells, suggesting that the synergy patterns of these kinases is common across these cancer types." (PMID 24068907, 2013). "Last, approved anti-cancer drugs that inhibit AAK1 or GAK, dramatically inhibited core-AP2M1 binding, HCV assembly, and infectious virus production." (PMID 22916011, 2012). "Last, approved anti-cancer drugs that inhibit AAK1 or GAK not only disrupt core-AP2M1 binding, but also significantly inhibit HCV assembly and infectious virus production." (PMID 22916011, 2012). "CCNB1IP1, CCNC, CCND2, CDK5R2, CDK9, and GAK were upregulated in all three cancer regions." (PMID 33302383, 2020). "Thus, novel kinase targets of GAK in the nucleus are expected to be identified to elucidate the role of GAK in cancer cells." (PMID 29559659, 2018). "Notably, hormone-insensitive cancer cells (PC-3 and MDA-MB231) expressed GAK at higher levels than hormone-sensitive cancer cells (LNCaP and MCF-7)." (PMID 24971999, 2014). "Both GAK and AR localized to the nuclei of cancer cells in GAK-positive surgical specimens." (PMID 24971999, 2014). "The aim of this study was to identify a new factor that controls AR signaling indirectly in HRPC patients, and to examine whether GAK could be targeted for the therapy of not only HRPC but also other cancers with enhanced GAK expression." (PMID 24971999, 2014). "This study shows that GAK could be used as a target for not only the therapy of HRPC but also other cancers with enhanced GAK expression." (PMID 24971999, 2014).
cancer (continued). "In contrast, LARS and GAK proteins related to T cell apoptosis and inhibition of IL-12 mediated IFNγ production were linked to high PD-L1 inducing activities in the PDS cultures, in line with a primary cancer niche including T cell infiltration but suppressed cytotoxic activity." (PMID 40240529, 2025). "The regulation of GAK levels by OIP5-AS1 illustrates the dynamic impact of lncRNAs on post-transcriptional gene expression programs, including those that influence cancer and other diseases characterized by aberrant proliferation." (PMID 28472763, 2017). "For instance, GAK and ROS1 had a relatively low Z-score, but still these were considered to have an important role in the cancer survival and/or proliferation process when combined with the other selected kinases." (PMID 24068907, 2013). "GAK has been shown to be involved in the progression of cancer to AI, although this is not because GAK is a direct coregulator of AR." (PMID 35335890, 2022). "Moreover, in three independent patient samples, GAK and the AR did not colocalize with Ki-67, a cancer antigen that is found primarily in growing cells and is absent in resting cells." (PMID 24971999, 2014). "Eventhough AAK1 and GAK are not among the cancer targets of these compounds, they are very potently bound and inhibited by sunitinib or PKC-412 and erlotinib, respectively (with Kds of binding that are lower or comparable to the major cancer targets)." (PMID 22916011, 2012).
infection (5 papers, 2014 to 2025). The state of being infected such as from the introduction of a foreign agent such as serum, vaccine, antigenic substance or organism. "Furthermore, inhibition of AAK1 and GAK was shown previously to inhibit infection of many pathogenic viruses, highlighting them as potential targets for broad-spectrum antivirals." (PMID 39017647, 2024). "Inhibiting GAK kinase activity by using erlotinib barely inhibited ERA-mCherry infection in HEK293, SK cells, and mPN cells." (PMID 31905947, 2019). "We found that AAK1 is essential for TOSV infection while GAK appears to play a less critical role, as evidenced by the increased infection levels observed at a higher MOI in shGAK cells but not in shAAK1 cells and the lack of effect of erlotinib." (PMID 39017647, 2024). "However, the influence on rabies virus differs, as GAK siRNA does not alter infection." (PMID 39017647, 2024).
tumor (5 papers, 2005 to 2022). "Our data also support the potential use of GAK inhibitors in triple-negative FBXW7-deficient tumours." (PMID 28829765, 2017). "GAK overexpression was identified in over 90% of androgen independent (AI) tumor biopsies from PC patients; a positive correlation between GAK expression and the Gleason score in surgical specimens from PC patients was reported." (PMID 35335890, 2022). "For example, lnc-OIP5-AS1 is shown to be a tumor suppressor and inhibit HeLa cells proliferation by interacting with the RBP HuR to reduce HuR’s availability for binding target mRNAs, or associating with GAK mRNA to impair GAK mRNA stability." (PMID 30699189, 2019).
neurodegenerative disease (3 papers, 2010 to 2021). A disorder of the central nervous system characterized by gradual and progressive loss of neural tissue and neurologic function. "As GAK is recently implicated in familial Parkinson disease, our results should provide a useful model for further understanding the cause of this neurodegenerative disease." (PMID 20082716, 2010). "The linkage of GAK to mitophagy is of particular relevance to neurodegenerative disease as SNPs in GAK have previously been identified as a risk factor for familial PD25 and expression changes in GAK are observed in the substantia nigra of PD patients." (PMID 34671015, 2021).
neurodevelopmental disorder (2 papers, 2022 to 2025). A behavioral and cognitive disorder with onset during the developmental period that involves impaired or aberrant development of intellectual, motor, or social functions. "The novel findings of the present study demonstrated that reduced GAK function is associated with neurodevelopmental disorders as well as α-synuclein-mediated neurodegeneration." (PMID 35883152, 2022).
movement disorder (1 paper, 2017). Neurological conditions resulting in abnormal voluntary or involuntary movement, which may impact the speed, fluency, quality and ease of movement. "Other genes, such as GAK, HTT, TMEM175, FAM193A, and DGKQ, were mainly related to movement disorders (adjusted p-value = 0.0001) and basal ganglia disease (adjusted p-value = 3.73e-05)." (PMID 28118382, 2017).
GAK also shares sentences with these, for which no sentence is quoted: non-small cell lung carcinoma (4 papers); Huntington disease (2); leukemia (2); lymphoma (2); adolescent idiopathic scoliosis (1); Alzheimer disease (1); autoimmune disease (1); Azoospermia (1); B-cell non-Hodgkin lymphoma (1); chronic myelogenous leukaemia (1); co-infection (1); cognitive decline (1); dementia (1); focal segmental glomerulosclerosis (1); gastrointestinal stromal tumour (1); hepatitis C (1); invasive carcinoma (1); ischemic stroke (1); kidney failure (1); leprosy (1); liver cancer (1); lung squamous cell carcinoma (1); myeloma (1); myeloproliferative neoplasm (1); neurological diseases (1); renal cell carcinoma (1); scoliosis (1); stomach cancer (1); Stroke (1).